RANBP17 (RAN binding protein 17)
Description:
May function as a nuclear transport receptor.
Tractability: PROTAC: ubiquitination databases record sites on it.
Gene: Protein-coding gene on chromosome 5 (170,861,870 to 171,300,015, forward strand). Ensembl gene ENSG00000204764.
Subcellular location: Cytoplasm; Nucleus; Nucleus, nuclear pore complex
Subcellular location (Human Protein Atlas): Nuclear bodies; Nucleoplasm; Cytosol; Nuclear membrane
Gene Ontology:
Molecular function: GTP binding; nuclear export signal receptor activity; small GTPase binding
Biological process: protein export from nucleus; protein import into nucleus; intracellular protein transport; nuclear transport; nucleocytoplasmic transport
Cellular component: cytoplasm; nuclear pore; nucleus
Genetic constraint (gnomAD): Loss-of-function variants: 76 observed, 66.64 expected, observed/expected ratio (o/e) 1.14, 90% interval 0.95 to 1.38. The upper end of that interval is the gene's LOEUF score, 1.38, which puts it in group 5 of 6, group 1 being the genes least tolerant of losing a copy. Missense variants: 801 observed, 786.54 expected, observed/expected ratio (o/e) 1.02, 90% interval 0.96 to 1.08. Synonymous variants: 280 observed, 295.66 expected, observed/expected ratio (o/e) 0.95, 90% interval 0.86 to 1.05.
Homologues: Orthologues: chimpanzee RANBP17 (99% identical), macaque RANBP17 (98% identical), dog RANBP17 (96% identical), pig RANBP17 (96% identical), rabbit RANBP17 (96% identical), rat Ranbp17 (94% identical), mouse Ranbp17 (94% identical), guinea pig RANBP17 (94% identical), Drosophila melanogaster Ranbp16 (54% identical), Caenorhabditis elegans C35A5.8 (40% identical). Paralogues in human: XPO7 (67% identical), XPO4 (21% identical).
Diseases named in the same sentence as RANBP17 in open-access papers:
RANBP17 is named in the same sentence as 15 diseases in open-access papers, as found by Europe PMC text mining. Sharing a sentence is not in itself a finding about the gene and the disease. The quoted sentences say what the papers report.
glioma (4 papers, 2017 to 2021). A benign or malignant brain and spinal cord tumor that arises from glial cells (astrocytes, oligodendrocytes, ependymal cells). "We also validated the expression pattern of two upregulated (METTL1 and OAS1) and three downregulated genes (KHDRBS2, RANBP17 and ELAVL3) in glioma cell lines using qRT-PCR." (PMID 28035070, 2017). "Collectively, these results conclude that downregulation of KHDRBS2, RANBP17 and ELAVL3 in glioma is indeed due to DNA methylation." (PMID 28035070, 2017).
dilated cardiomyopathy (2 papers, 2015 to 2019). Cardiomyopathy which is characterized by dilation and contractile dysfunction of the left and right ventricles. "Expression of RANBP17 has been detected in many human and mouse tissues, including brain, heart, lung, pancreas, placenta, and testis, with the highest levels of expression in testis, and levels of RANBP17 mRNAs increases with ischemic and dilated cardiomyopathy." (PMID 26580069, 2015).
glioblastoma (2 papers, 2022 to 2025). The most malignant astrocytic tumor (WHO grade IV). "Notably, circRANBP17, a circular RNA derived from RANBP17, has been shown to promote tumour progression via miRNA sponging mechanisms, and RANBP17 itself has been implicated in nuclear transport and immune modulation associated with miRNAs in glioblastoma." (PMID 41397929, 2025).
head and neck squamous cell carcinoma (1 paper, 2022). A squamous cell carcinoma that arises from any of the following anatomic sites: lip and oral cavity, nasal cavity, paranasal sinuses, pharynx, larynx, and salivary glands.
nasopharyngeal carcinoma (1 paper, 2022). A carcinoma arising from the nasopharyngeal epithelium. "In a recent study by Zhou and coworkers, the authors identified a RanBP17 derived circular RNA (circRanBP17) that is implicated in the pathogenesis of nasopharyngeal cancer." (PMID 35850701, 2022). "The recent discovery of circRanBP17 RNA and its implication in nasopharyngeal cancer prompted us to look at a possible involvement of circRanBP17 in the RanBP17 effects observed in our study." (PMID 35850701, 2022).
T-cell acute lymphoblastic leukemia (1 paper, 2017). Acute lymphoblastic leukemia of T-cell origin. "In human, RANBP17 is the loci of recurrent chromosomal 5 breakpoints detected in T-cell acute lymphoblastic leukemia, and the transcriptional activation of this gene occurs during hematopoietic process with enhancer elements of the TCR delta gene." (PMID 28499406, 2017).
cancer (5 papers, 2010 to 2025). A tumor composed of atypical neoplastic, often pleomorphic cells that invade other tissues. "Based on the single‐cell sequencing derived from NPC clinical samples, RANBP17 is expressed in EBV‐associated NPC cells, KCNJ10 is detectable in myeloid cells, and CXCR5 is dormantly expressed by B cells, while cancer‐associated fibroblasts mainly express CCL19 and CCL21." (PMID 41397929, 2025). "We speculate that RANBP17 may suppress stromal CXCL13, CCL19 and CCL21 through exosome‐mediated mechanisms by reprogramming the cargo of cancer‐derived exosomes to include regulatory RNAs and proteins." (PMID 41397929, 2025).
tumor (4 papers, 2020 to 2025). "In this context, it is very tempting to implicate recently discovered circRanBP17 RNA species as products of the RanBP17 gene, which are implicated in tumor growth." (PMID 35850701, 2022). "Since HPV+ HNSCC are frequently associated with high levels of tumor infiltrating leukocytes (TILs), the observed RanBP17 overexpression could also be derived from TILs present in the tumor." (PMID 35850701, 2022). "Here, we hypothesize that, in contrast to tissues (including tumor tissues) cultured cell lines exhibit a markedly increased cell proliferation and cell turnover rate, which either requires expression of additional RanBP17 splice variants or leads to increased degradation of RanBP17." (PMID 35850701, 2022). "RanBP17 expression was monitored after inhibiting tumor cells with CDDP or with the EGFR kinase inhibitor AG1478." (PMID 35850701, 2022). "To evaluate the RanBP17 expression levels of different cell types present in the tumor tissue, we used existing single cell RNAseq (scRNAseq) data sets." (PMID 35850701, 2022). "Comparing tumor tissues with normal controls frequently revealed significantly different RanBP17 expression levels between the tested tissues." (PMID 35850701, 2022). "Similarly, inhibiting cell proliferation with cisplatin reduced RanBP17 in keratinocytes but lead to induction in tumor cell lines." (PMID 35850701, 2022). "To evaluate, if HPV positivity of a tumor could affect RanBP17 expression in TILs, we looked into another dataset, which included scRNAseq data from HPV- and HPV+ HNSCC derived immune cells." (PMID 35850701, 2022). "Next, we explored circRANBP17 in NPC progression, and revealed that circRANBP17 down-regulation blocked cell proliferation, invasion in vitro, colony formation and tumor growth in vivo, suggesting RANBP17 may have carcinogenic functions during NPC progression." (PMID 34093832, 2021). "Next, we tested whether sh-circRANBP17 exerted biological functions by promoting cell growth in vivo; RANBP17 suppression significantly reduced tumor growth in nude mice when compared to the control group." (PMID 34093832, 2021). "In our study, we observed a major role of RanBP17 in HNSCC cell proliferation, which was also noted in cell lines derived from other tumor types." (PMID 35850701, 2022). "In contrast to tumor cell lines, CDDP treatment of NHEK resulted in reduction of RanBP17 levels." (PMID 35850701, 2022). "Furthermore, RanBP17 RNA expression levels were monitored by RT-qPCR in HCT116p53 wt/wt and UM-SCC-3 tumor cell lines after treatment with 0.78, 1.56, 3.13, 6.25, 12.5, 25, 50 and 100 μmol/L CDDP using eleven (P1-P11) RanBP17 specific primer pairs." (PMID 35850701, 2022). "Immune cells exhibit only low RanBP17 expression levels and therefore do not appear to account for the elevated RanBP17 levels in tumor tissues with high TIL levels as found in HPV+ HNSCC." (PMID 35850701, 2022).
RANBP17 also shares sentences with these, for which no sentence is quoted: autism (1 paper); cardiomyopathies (1); head and neck cancer (1); hyperglycaemia (1); Insulin resistance (1); ischemic cardiomyopathy (1); neurodevelopmental disorder (1).